CXCR4 (C-X-C motif chemokine receptor 4)
Diseases named in the same sentence as CXCR4 in open-access papers (continued):
Sharing a sentence is not in itself a finding about the gene and the disease.
tumor (continued). "Finally, they demonstrated that hBMSC-derived exosomes could increase VEGF and CXCR4 expression in tumor cells by ERK1/2 and p38 MAPK pathways activation, leading to enhanced angiogenesis, thus promoting tumor growth in vivo." (PMID 34479611, 2021). "Studies on tumor cell biology indicated that the interaction between C-X-C motif chemokine receptor 4 (CXCR4) and its chemokine ligand 12 (CXCL12; also known as stromal cell-derived factor 1, SDF-1) plays an essential role in cell oncogenesis and development of metastatic lesions in tumor." (PMID 34070538, 2021). "While some migrated tumor cells highly express CXCR4, cells of other origin do not." (PMID 33467498, 2021). "Moreover, TF ETS1 could activate target genes CXCR4 and ZEB1 to trigger metastasis mediated by downstream core signaling cascades through the suppression of tumor inhibitor, miRNA MIR497." (PMID 33802957, 2021). "Another phase I/II trial (NCT01977677), aiming at studying the safety and efficacy of the CXCR4 inhibitor plerixafor, after chemo/radiotherapy with the chemotherapeutic agent temozolomide (TMZ), suggests CXCR4-targeting as beneficial for patient survival and local control of tumor recurrence." (PMID 35008294, 2021). "In addition, among the surface MIF receptors, surface expression of CXCR2 and CXCR4 in M-MDSC, and CXCR4 and CXCR7 in G-MDSC were decreased in response to rSmeg-hMIF-hIL-7, indicating that rSmeg-hMIF-hIL-7 suppressed the infiltration of MDSC into tumor." (PMID 34389619, 2021). "Importantly, the overall expression of CXCR4 on blood neutrophils from tumor-bearing mice was significantly higher compared with non-diseased animals, whereas the proportion of chronologically aged neutrophils of total neutrophils remained stable." (PMID 34876407, 2021). "In the therapeutic model, upon animal sacrifice, the tumor masses were excised and subjected to qRT-PCR analysis of the human and mouse genes in order to assess the effects of the RGZ and MTT in vivo treatment on the CXCL12/CXCR4/CXCR7 axis and tumor vascularization." (PMID 34834449, 2021). "However, a significant correlation was not reached between the expression levels of CXCR-4 and stage, age, location of the tumor as well as sex." (PMID 34885003, 2021). "Indeed, among several cytokines that regulate the tumor-bone interaction and were upregulated significantly more by KLF5KQ than by KLF5KR (SHH, WNT5A, IL11, and IL6), the induction of IL-11 was dependent on CXCR4 expression." (PMID 33731701, 2021). "As inhibition of TLR4, CXCR4 and CCR7 impacted anti-tumor immunity and reduced tumorigenesis (tumor numbers, growth and metastasis), our novel OSCC13 grafting model may be suitable to investigate these and other alternative targeting approaches in particular in combination with radiotherapy." (PMID 34290694, 2021). "In addition, immunohistochemistry on tumor sections from the xenograft models showed that both individual treatment and co-treatment decreases the protein expression levels of Ki-67, VEGFR, MMP9, HIF1-α and CXCR4 compared to control tumors." (PMID 33673143, 2021). "EPCs are recruited into ischemic or hypoxic tumours predominantly in response to chemokines (e.g., CXCL12, CCL2, CCL5) and growth factors (e.g., VEGF, bFGF), which interact with their respective receptors (e.g., CXCR4, CCR2, CCR5, VEGFR2) on the surface of EPCs." (PMID 34035882, 2021). "Due to this dramatic down-regulation in chemokine receptors’ expression on TANs, we hypothesized that the chemokines binding CXCR2 and CXCR4 (i.e., CXCL1/CXCL2 and CXCL12, respectively) could be responsible for the differential infiltration of NDN and LDN into the tumor." (PMID 34680231, 2021). "In the current study, we explored the potential mechanism of Porf-2 in tumor cell migration by screening several key proteins, such as adhesion molecules (ICAM1, VCAM1, E-cadherin), chemokines (CCL4, CXCL4) and their receptors (CXCR4/6/7), integrins (integrin α1/β1/β3), and MMPs (MMP-2/3/7/9)." (PMID 32676454, 2020).
tumor (continued). "However, whether the expression of CXCR4 is correlated with the TMB, CYT, immune infiltration, and tumor purity of GC is still unknown." (PMID 32306562, 2020). "More recently, some studies have demonstrated that CXCR4 inhibition can reduce immunosuppression both by acting on Treg cells and myeloid derived suppressor cells (MDSC) that highly expressed CXCR4 receptor, overall resulting in the reactivation of T immune response against tumor cells." (PMID 33123122, 2020). "Moreover, during the process of CTCs avoiding anoikis to attach to the endothelium, CTC chemokine receptors CXCR4 and CCR7 bind to CXCL12 and CCL21 on endothelial cells to mediate tumor cell arrest and to resist anoikis by regulating the proapoptotic and antiapoptotic Bmf and Bcl-xL proteins." (PMID 32943996, 2020). "Interestingly, the normal tissue adjacent to the CXCR4 overexpressing tumor shows normal or no CXCR4 expression, which suggests a differential response of cancer cells to microenvironmental conditions." (PMID 32983169, 2020). "In addition, tumor-derived CCL2 can directly act on CCR2 positive endothelial cells to increase their permeability or indirectly via increasing CXCL12 expression, which helps CXCR4 positive cancer cells to extravasate into the PMNs." (PMID 33414786, 2020). "Positive CXCR4 expression was found in 195 (79.9%) samples of tumor tissues and 12 (4.9%) samples of normal tissues, while positive cases for CXCR5 and CCR7 were 155 (63.5%) and 117 (48.0%) samples of tumor tissues and 15 (6.1%) and six (2.5%) samples of normal tissues, respectively." (PMID 32896997, 2020). "However, clinical trials combining a CXCR4 antagonist with pembrolizumab failed to reduce patients’ tumor burden during treatment." (PMID 33198059, 2020). "Combination therapy using anti-PD-1 antibody and an inhibitor of CXCR4, a receptor for CXCL12/SDF-1 that contributes to the maintenance of tumor stem cells, also increases local infiltration of CD4/8 T cells by suppressing Treg and MDSC tumor invasion and prolongs the survival of tumor-bearing mice." (PMID 32707672, 2020). "Accordingly, administering an inhibitor of CXCR4, the receptor for CXCL12, to the PDA-bearing mice led to the rapid accumulation of effector T cells within the tumor and blockage IL-6 could improve T-cell trafficking, migration and tumor immunosuppression." (PMID 33613544, 2020). "The tumor-restricting activities of CXCR7/ACKR3 may be connected to the fact that unlike CXCR4, it is an atypical chemokine receptor (and thus was given the additional name ACKR3)." (PMID 32582148, 2020). "When tested in vivo actein significantly inhibited blood vessel formation and decreased tumor size and metastasis through reducing the expression of angiogenic proteins (CD34 and Factor VIII) and metastasis-related VEGFR1 and C-X-C chemokine receptor type 4 (CXCR4) genes." (PMID 33552000, 2020). "We also could not investigate an equal number of tumor samples for both CXCR4 and CXCR7 and only had access to a limited pool of metastases and local recurrences unrelated to the primary tumors." (PMID 33281749, 2020). "Thus, the high T22-PE24-H6 nanoparticle tumor uptake may take advantage of the EPR effect, the discontinued endothelia in the relevant clinical organs and the active targeting to high CXCR4 overexpressing DLBCL cells." (PMID 32373205, 2020). "ENSAT tumor stage did not correlate with the staining intensity of CXCR4 or CXCR7." (PMID 33281749, 2020). "Finally, the tumor vasculature has also been targeted by OVV-CXCR4-A-mFc, a VV expressing a CXCR4 antagonist, which is directed against the VEGF-induced pro-angiogenic CXCL12/CXCR4 signaling pathway in human breast tumor cells." (PMID 33167307, 2020). "CXCR4 expression was detected in single cells, rather than clusters of cells, throughout the tumor." (PMID 32066735, 2020). "However, in the prior studies, it was not determined if CXCR4 overexpression correlated with CXCR4 in tumor colonocytes and/or in tumor stromal cells." (PMID 32110952, 2020).
tumor (continued). "We focus on ACKR1 (DARC), ACKR3 (CXCR7), CXCR4, and CCR2, as these are the best studied chemokine receptors in TEC; and suggest that targeting these receptors on the tumor vasculature may prove efficacious in slowing or reversing tumor growth." (PMID 30800123, 2019). "HIF proteins induce the expression of several genes involved in tumor phenotypes, such as platelet-derived growth factor (PDGF), transforming growth factor alpha and beta (TGF-α, TGF-β), matrix metallopeptidase 1 (MMP1), C-X-C chemokine receptor type 4 (CXCR4)." (PMID 30708988, 2019). "Cells were treated with anti-CXCR4 antibody for 30 min at 4° C and then with normal human serum (NHS), or heat inactivated normal human serum (HIS), plus or minus SMR peptides for 60 min at 37° C. In the presence of NHS, both of SMRwt peptides significantly induced tumor cell death via complement." (PMID 31534628, 2019). "Furthermore, tumor exoRNAs can activate lung epithelial cell TLR3 to recruit neutrophils due to the expression of chemokine receptors (CXCR1, CXCR2, CXCR4, andCCR2) being higher in tumor-bearing Tlr3−/− mice, consequently inducing lung premetastatic niche formation." (PMID 30849983, 2019). "A strong understanding of how tumor cells respond to heightened flows over a range is important to an understanding of the implications of CED and perhaps implementation of therapies (such as CXCR4 inhibitors or CD44 inhibitors) that can attenuate these responses." (PMID 31632905, 2019). "Chen and co-workers have demonstrated that prolonged sorafenib treatment heightens tumor hypoxia, and increases expressions of CXCR4 and SDF-1α in HCC, which indicates that down-regulation of CXCR4 level or intervention of SDF-1/CXCR4 signaling pathway may overcome sorafenib resistance and evasion." (PMID 31151472, 2019). "The lead ADC presents a novel MoA that: 1) limits tumour and leucocyte mobilization, 2) reduces antigen-dependent ADC clearance (as shown by the enhanced exposure in HuCXCR4KI mice) and 3) mitigates toxicity to quiescent CXCR4+ normal tissues, including HSC/LSK progenitors." (PMID 30792442, 2019). "Notably, CXCR4-positive lumen structures were found in the tumor area, although not in the nontumor area." (PMID 31336612, 2019). "To investigate whether CXCR4 expression in vessels could be different between tumor and nontumor areas in OSCC clinical cases, we first defined the tumor and nontumor areas in the OSCC specimens." (PMID 31336612, 2019). "We, therefore, asked whether and how CXCR4 antagonism could disrupt structures of blood vessels occupied by viable (non-necrotic) tumor cells." (PMID 31336612, 2019). "The involvement of CXCR4 in tumor progression is not restricted to tumor cells." (PMID 31921628, 2019). "Interestingly, although MDM2 promotes the cancer cell release from the primary tumor into the circulating system, the observed downregulation of CXCR4 or PTGS2 expression by MDM2 knockdown was not statistically significant." (PMID 30642351, 2019). "For example, since CXCR4 is upregulated on immune suppressive regulatory CD4+ T cells, targeting CXCR4 could diminish these immune checkpoint cells and potentially unleash a potent anti-tumor immune response." (PMID 30800123, 2019). "This is relevant, because CXCL12 and its receptor CXC chemokine receptor 4 (CXCR4) are present in complex lesions in PAH and CXCL12 promotes aberrant angiogenesis, endothelial proliferation and PH while others have found Wnt1 to be protective from aberrant tumor angiogenesis." (PMID 30883593, 2019). "However, there is another report in which inhibition of CXCR4 primarily blocks PC trafficking to bone without influencing tumor growth." (PMID 29930538, 2018).
tumor (continued). "However due to its strong myeloablative effect CXCR4-directed radionuclide therapy seems not to be of clinical value in this tumor entity." (PMID 29721166, 2018). "An invasive growth pattern due to CXCR4 overexpression could explain why hearing impairment does not always correlate with tumor size." (PMID 29515781, 2018). "Compared to SDF1 expression levels, the expression levels of CXCR4 in F cells and corresponding transplanted tumor tissues were increased to a greater extent than that in normal liver cells, P cells and normal liver tissue as well as corresponding transplanted tumors." (PMID 29783989, 2018). "Moreover, the presence of CXCR4 expressing CD4+CD45RA+ T cells correlated with absence of primary tumor ulceration." (PMID 30420855, 2018). "Importantly, irradiation has been shown to induce SDF-1 expression and thus may boost vasculogenesis and tumor re-growth after end of therapy suggesting a radioresistance-conferring action of SDF-1/CXCR4 signaling as discussed in the next paragraph." (PMID 30622535, 2018). "In addition, we found a significant increase in Cxcl12 expression in CHOP-treated group but not in its receptor Cxcr4, being relevant, since the CXCL12–CXCR4 axis has been associated with tumor invasion and metastases." (PMID 29410666, 2018). "Furthermore, inhibition of CXCL12 with the L-RNA-aptamer NOX-A12, which impedes CXCL12 interaction with CXCR4 and CXCR7, led to greater tumor infiltration by T and natural killer (NK) cells with an improved anti-PD1 therapy in a mouse model of colorectal cancer." (PMID 30420856, 2018). "We conclude that CXCR4 is not a marker for the tumor extension but may be relevant for tumor invasiveness, as reflected by hearing impairment." (PMID 29515781, 2018). "Therefore, we propose that GFAP/CD90+/CD44+ EPN cells correlate with the expression of CD133, nestin, CXCR4 and SSEA-3, which could act as markers of enrichment for tumor-initiating cells." (PMID 29774098, 2018). "The knockdown of AIB1 greatly reduced CXCR4 gene expression at both the transcription and protein levels, whereas the knockdown of CXCR4 in cells with AIB1 ectopic overexpression diminished AIB1-induced migration and invasion in vitro and tumor metastasis in vivo." (PMID 30103827, 2018). "In tumours within or close to the central nervous system (CNS), however, due to its better contrast characteristics compared to [18F]FDG PET, the CXCR4-directed tracer [68Ga]Pentixafor may improve the current response criteria provided by the International Primary CNS Lymphoma Collaborative Group." (PMID 28577295, 2017). "However, since CXCR4 blockade also amplified the effect of sunitinib on the tumor growth, this provides extra evidence that the SDF-1α/CXCR4 axis plays a major role in promoting tumor growth." (PMID 28057017, 2017). "As suggested by the low IRS, a possible explanation for the limited [68Ga]Pentixafor tumor uptake could be that CXCR4 might not always or only in parts be expressed on the cell surface (being a crucial prerequisite for successful PET imaging)." (PMID 29221153, 2017). "In addition, C/EBP-δ regulates gene expression, including VEGFR3 in lymphatic endothelial cells, platelet-derived growth factor receptor (PDGFR) in vascular smooth muscle cells, insulin-like growth factor-I in osteoblast cells, CXCR4 and HIF-1α in tumor cells and macrophages." (PMID 28881585, 2017). "However, clinical data on the cell membrane expression of CXCR4 and its relation with tumor invasiveness is still lacking." (PMID 28549419, 2017). "Interestingly, we observed that murine peritumoral stroma expressed CXCR4 but not CXCL12 in the two tumour xenografts." (PMID 28386296, 2017). "Furthermore, systemic treatment of SIS3 also significantly altered the tumour-friendly microenvironment, including suppression on angiogenesis (VEGF expression and CD31+ vessels) and tumour-invasive factors (MMP-2, MMP-9, MMP-13 and CXCR4)." (PMID 28262747, 2017).
tumor (continued). "Importantly, it was found that SS cultures contain a subpopulation of cells expressing high levels of CXCR4 that also express high levels stem cell markers (NANOG, OCT4, SOX2), and these cells have an increased tumor initiating capacity in xenographic mouse models." (PMID 28191313, 2017). "In addition, CXCR4 promotes the secretion of matrix metalloproteinases (MMPs), such as MMP2 and MMP9, which leads to the degradation of extracellular matrix (ECM) and facilitates the tumor cell motility." (PMID 28793338, 2017). "As shown in TACs, tumor uptake was higher than activity accumulation in all other tissues already at 17 min p.i., highlighting the efficient CXCR4-targeting and fast clearance of the tracer from non-target tissue with comparably low unspecific background accumulation at all time points." (PMID 29527563, 2017). "In addition, SKCXCR2-derived tumor tissues maintained high CCL20 mRNA expression and induced greater CCL24 and CXCR4 compared to SKCXCR2 cells, indicating the shift of chemokine network during the peritoneal spreading of tumor cells via interaction with other cell types in tumor microenvironment." (PMID 27723802, 2016). "While this fact does not negatively affect the final quality (tumor-homing) and organization (self-assembling) of complex smart materials such as CXCR4-targeted protein nanoparticles, it indeed influences some of their relevant properties at the macroscopic level." (PMID 27059706, 2016). "In addition to CXCR4 and CXCR7 mRNA levels, other differences in gene expression between MDA-MB-231-B and MDA-MB-231 might be present and influence tumor cell behavior." (PMID 26744352, 2016). "However, we found that the CXCR4 level in tumor tissues was actually higher than that in adjacent non-tumorous tissues, and enhanced expression of CXCR4 was also reported to be associated with poor diagnosis in other malignant tumors." (PMID 27835898, 2016). "Next, we examined by qRT-PCR if FOXC2 knockdown in U2OS cells affects the expression of several genes known to be enriched in tumor-propagating cells, such as the cell surface marker CD133, multidrug resistance pump ABCG2, Notch signaling receptor ligands JAG1 and BMP4, and chemokine receptor CXCR4." (PMID 27634875, 2016). "In chronic lymphocytic leukemia (CLL) cells, SDF1 produced by stromal cells can interact with CXCR4 and activate extracellular signal-regulated kinase 1/2 (ERK1/2) and Akt (also known as protein kinase B (PKB)) pathways, leading to anti-apoptotic responses and promoting tumor cell survival." (PMID 27270649, 2016). "There was no relation between preoperative tumor size and CXCR4 or CXCL12 expression." (PMID 26920352, 2016). "Conversely, CXCR4 blockade did not affect the accumulation of tumor-infiltrating MDSCs or Tregs." (PMID 27590504, 2016). "CXCR4 expression was stronger in the xenograft tumor containing CAFs compared to tumors without fibroblasts or containing NFs and increased gradually in endometrial tissues as they progressed from NE to HE to AHE and finally to EC tissues (χ2 = 139.485, P = 0.000)." (PMID 26851944, 2016). "This hypothesis is supported by the low expression level of CD133 and CXCR4 in U0126-pre-treated cells and correlates strongly with the delay in tumor development that occurred without any further U0126 being added." (PMID 26897742, 2016). "Additionally, CXCR4 is highly overexpressed in SCLC and at least 23 other tumor entities." (PMID 27835905, 2016). "Due to its negative effect on CXCR4 expression, tumor intrinsic CXCL12 may be a valuable biomarker in clinical situations that require decision-making." (PMID 27462860, 2016). "In addition, a correlation between CXCR4 expression and therapeutic response was observed in NSCLC and TNBC tumor models, suggesting that CXCR4 imaging could be used for identification of tumors most responsive to CXCR4-targeted therapies." (PMID 26848769, 2016).